ZEB1 (zinc finger E-box binding homeobox 1)
Diseases named in the same sentence as ZEB1 in open-access papers (continued):
Sharing a sentence is not in itself a finding about the gene and the disease.
breast carcinoma (continued). "Such pro‐apoptotic mechanism mediated by TIMP3 overexpression may explain the observed anti‐proliferative and reduced anchorage‐independent growth of the breast cancer cells where ZEB1 was eliminated, thus subsequently causing upregulation of endogenous TIMP3 expression." (PMID 29744893, 2018). "It opens the possibility of identifying ZEB1 target genes, which may allow interference with their function and generate, together with ZEB1 loss of function approaches, synthetic lethality that eliminates breast cancer cells." (PMID 29744893, 2018). "SIGLEC15 inhibits the EMT pathway and modulates the biological behavior of breast cancer cells by regulating ZEB1 expression." (PMID 41158758, 2026). "Notch also induces ZEB1, N-cadherin, and fascin expression, and evidence from pancreatic cancer suggests that a Notch → Akt → fascin axis likely operates in breast cancer." (PMID 40806254, 2025). "It is reported that LincK can regulate the expression of ZEB1 and the function of miR-200 in breast cancer." (PMID 41211430, 2025). "EMT and its associated stem cell-like phenotype are considered major causes of breast cancer resistance, especially the EMT activator ZEB1, which has been shown to have stemness and therapy resistance." (PMID 40046628, 2025). "MiR-200c restored the sensitivity of HER2-positive breast cancer to trastuzumab by targeting ZNF217/TGF-β/ZEB1 axis and suppressing CSC-like phenotype." (PMID 41211430, 2025). "ThPOK-kd led to an increase in the expression of EMT factors (VIM, SNAI2, ZEB1, ZEB2), basal markers and WNT/β-catenin target genes implicated in breast cancer cell proliferation." (PMID 41231242, 2025). "In breast cancer, ZEB1 can also activate the ATM promoter by binding to p300/pCAFj, forming a positive feedback loop that promotes DNA repair and resists DNA damage caused by chemotherapy." (PMID 41211430, 2025). "ZEB1 is a key inhibitor of transcription upstream of CDH1, and we identified significant downregulation of ZEB1 targets compared to ZEB1 targets identified by knockdown of ZEB1 in breast cancer cells." (PMID 40717170, 2025). "There are many known targets of miR-205 in breast cancer, including transcription factors ZEB1, ZEB2 and SIP1, which are responsible for regulating EMT." (PMID 41211430, 2025). "In basal-like breast cancer, we found that a low WWOX/HIF1A ratio is associated with particularly aggressive disease because it promotes EMT via ZEB1 and ADAM9, facilitates ECM remodelling via MMP2 and ITGA1, and enables immune evasion via NOTCH1 and TLR4." (PMID 41007296, 2025). "While ZEB1 expression in breast cancer stem cells increased five-fold compared to MCF-7 cells without BA, it decreased almost 5-fold in cells applied to cancer stem cells without BA." (PMID 38963646, 2025). "MiR-200c is a critical regulator in the metastatic progression of various cancers, particularly breast cancer, by modulating ZEB1 and ZEB2, which in turn influence the EMT process." (PMID 39859424, 2025). "EMT transcription factors such as SNAIL and ZEB2 can inhibit cell cycle transition by inhibiting the transcription of CCND2 and CCND1, respectively, ZEB1 protein degradation induced by CDK4/6 inhibition blocks breast cancer metastasis." (PMID 39949984, 2025). "This significantly distinguishes UM from breast cancer, where ZEB1-positive tumor cells are of a mesenchymal high-proliferative phenotype." (PMID 41226394, 2025). "In a previous study, we demonstrated that M13HS tumor hybrids, derived from human M13SV1-EGFP-Neo breast epithelial cells and human HS578T-Hyg breast cancer cells, exhibited co-expression of Snail and Zeb1." (PMID 40806166, 2025). "In breast cancer cells, the interaction of Zeb1 and CD44s increased tumor-sphere initiation capacity, drug resistance, and tumor recurrence." (PMID 40806166, 2025).
breast carcinoma (continued). "M13HS-2/-8 tumor hybrid clones derived from human M13SV1-EGFP-Neo breast epithelial cells and human HS578T-Hyg breast cancer cells exhibited co-expression of Snail and Zeb1." (PMID 40806166, 2025). "Our results regarding the immunohistochemical test with ZEB1 and visual analysis showed that this protein is indeed present in both benign and malignant mammary tumors of bitches." (PMID 40005870, 2025). "NOTCH3 maintains the luminal phenotype and inhibits epithelial-mesenchymal transition (EMT) in breast cancer, while ZEB1 and NOTCH3 have the opposite effects." (PMID 38164285, 2024). "A low level of NOTCH3 or high level of ZEB1 was correlated with poor overall survival (OS) of patients with breast cancer, with HR = 0.88, p = 0.0095 and HR = 3.93, p = 0.023, respectively." (PMID 38164285, 2024). "Quantitative gene expression analysis was performed to assess the transcription of EMT (epithelial–mesenchymal transition) markers Slug, Snail, Twist2, and Zeb1 in trastuzumab-resistant HER2-positive breast cancer cells." (PMID 39201327, 2024). "There is increasing evidence that ZEB1 plays a role in the initiation and progression of breast cancer." (PMID 39196911, 2024). "Due to the lack of western blotting analysis data, our results cannot confirm the effect of ribociclib on ZEB1 expression in breast cancer cell lines." (PMID 39196911, 2024). "Clinically, high expression of NOTCH3, miR-223 or low expression of ZEB1 were related to good prognosis of breast cancer patients." (PMID 38164285, 2024). "It is reported that YEATS4 regulates the expression of ZEB1 in breast cancer, promotes EMT and metastasis, and is related to poor prognosis." (PMID 38164285, 2024). "MiR-223 inhibited the proliferation and invasion of breast cancer cells via down-regulating the expression of ZEB1." (PMID 38164285, 2024). "It was found that the expressions of NOTCH3 and ZEB1 in breast cancer cells were negatively correlated." (PMID 38164285, 2024). "AP-1 motif was found enriched at ZEB1 binding sites and the AP-1 subunit FOSL2 was shown to co-occupy similar loci with ZEB1, suggesting a cooperation of ZEB1 with AP-1 in melanoma, in line with data in breast cancer cells." (PMID 38519642, 2024). "The current study aims to evaluate the correlation between NOTCH3 and ZEB1 and investigate the potential regulatory axis in breast cancer." (PMID 38164285, 2024). "USP51 depletion inhibited the invasion of mesenchymal-like breast cancer cells by downregulating ZEB1 protein and mesenchymal marker expression and promoting E-cadherin upregulation." (PMID 39196911, 2024). "Mechanically, breast cancer cells that ectopically express Zeb1 produce lactic acid in an acidic tumor environment and induce alternating activation of TAMs by stimulating the PKA/CREB signaling pathway." (PMID 39596288, 2024). "NF-κB increases EMT-associated genes SNAI1, TWIST1, ZEB1, and VIM in a variety of disease processes including pulmonary lung fibrosis and many cancers: head and neck, prostate, pancreatic, and breast cancer." (PMID 39348939, 2024). "Using reporter gene assays, miR-223 can directly bind to the 3'UTR of ZEB1 in breast cancer cells, indicating that miR-223 directly inhibits the expression of ZEB1." (PMID 38164285, 2024). "The Cancer Genome Atlas dataset (Pan-Cancer Atlas) from patients with breast cancer showed a significant positive correlation between AhR and ZEB1." (PMID 39311710, 2024). "Researchers Lu and colleagues have proven that restin can prevent EMT in breast cancer by binding to p73, activating miR-200a/b, and thereby decreasing the production of ZEB1/2, which are master transcription factors for EMT." (PMID 39850890, 2024). "The expression of commonly studied EMT markers (SLUG, SNAIL, TWIST1, ZEB1) correlated well with the poor prognosis in breast cancer patients." (PMID 37975220, 2024).
breast carcinoma (continued). "Studies in malignant tumors such as breast cancer and ovarian cancer have shown that the Zeb1/miR-200s axis is involved in the regulation of EMT by GRHL2." (PMID 39402063, 2024). "Breast cancer cells treated with calcitriol decrease the expression of ZEB1, N-cadherin, vimentin, or integrins and increase the level of E-cadherin, suggesting that calcitriol reduces the EMT process." (PMID 38360633, 2024). "Wu HT also revealed that ZEB1 had mesenchymal properties, increasing the proliferation, metastasis, and drug resistance of breast cancer cells." (PMID 38916621, 2024). "Cells of the innate immune system release IL-1β, which upregulates ZEB1 in breast cancer cells and induces growth arrest by EMT." (PMID 38419052, 2024). "A few studies have implicated a prognostic role for ZEB1 and ZEB2 in tumor types such as ovarian, colorectal, and breast carcinomas." (PMID 38719798, 2024). "There have been many reports about the high expression of ZEB1 and the poor prognosis of breast cancer patients." (PMID 38164285, 2024). "Inflammation of the lung can induce EMT of dormant breast cancer cells in a mouse model via the expression of ZEB1, resulting in reactivation of the dormant cancer cells." (PMID 38419052, 2024). "For example, bivalent chromatin configuration at the ZEB1 promoter enables breast cancer cells to respond readily to microenvironmental signals and enhances tumorigenicity." (PMID 38182582, 2024). "In the more aggressive basal subtype of breast cancer, cells maintain the Zeb1 promoter in a bivalent configuration, facilitating EMT induction." (PMID 38385532, 2024). "In pancreatic and breast cancer, ZEB1 was also found to be upregulated in the dysplastic fibroblast-rich stroma, which was correlated with poor survival." (PMID 38937629, 2024). "In breast cancer, downregulation of SLFN5 protein in breast cancer cells increases ZEB1 transcriptional activity." (PMID 37771431, 2023). "The findings reveal that ZEB1‐induced MIR497HG depletion contributes to breast cancer progression and tamoxifen resistance through PI3K‐AKT signaling." (PMID 36815359, 2023). "We next investigated the phenotypic consequences of ZEB1 silencing by the CRISPR/dCas9 systems in mesenchymal breast cancer cells." (PMID 37217832, 2023). "As a transcriptional repressor, SLFN5 prevents epithelial-mesenchymal transition (EMT) in breast cancer and targets the ZEB1 promoter to suppress ZEB1 transcription and downstream PTEN/AKT/cyclin D1 signaling cascade, ultimately inducing cancer cell death." (PMID 37771431, 2023). "Preliminary evidence suggests that epigenetic inheritance of the ZEB1 gene is related to breast cancer metastasis and recurrence." (PMID 37978168, 2023). "The colony formation capacity of the HS578T-Hyg ZEB1-KO breast cancer cells was about 50% lower than that of the HS578T-Hyg wildtype breast cancer cells." (PMID 38139138, 2023). "It was also shown that activation of the EMT program by loss of E-cadherin, mediated by upregulated EMT-TF Snail, Twist, or Zeb1, in breast cancer cells, induces Hedgehog signaling in the pathway involved in stemness induction." (PMID 37372954, 2023). "The ANTXR1 is expressed on metastatic breast cancer stem cells (CSCs) and functions in collagen signaling, as well as Wnt signaling, ZEB1 expression, and CSC self-renewal, invasion, tumorigenicity, and metastasis." (PMID 36769365, 2023). "For instance, stable knock-down of ZEB1 expression in the MDA-MB-231 breast cancer cells with specific ZEB1 shRNA, resulted in markedly elevated (about 800-fold) miRNA-200c expression levels." (PMID 38139138, 2023). "In a previous work, we studied the interactome of the Zeb1 transcription factor in MCF-7/Zeb1 breast carcinoma cells." (PMID 37372954, 2023).
breast carcinoma (continued). "USP51 was first shown to act as a cancer promoter by targeting ZEB1 for deubiquitination in breast cancer." (PMID 37422632, 2023). "Recent studies have shown that PTBP3 promotes epithelial–mesenchymal transition in breast cancer through the regulation of ZEB1 mRNA stability." (PMID 37633911, 2023). "Activation of EMT in breast carcinoma cell lines leads to the augmentation of TF expression, a phenomenon reversed by the silencing of ZEB1 (Zinc finger E-box-binding homeobox 1), a master regulatory factor of the EMT." (PMID 38201433, 2023). "When breast cancer cells are in the state of endocrine resistance, ZEB1 recruits DNMT3B and HDAC1/2 to the MIR497HG promoter region, which leads to transcriptional repression through DNA methylation and histone modification." (PMID 37901333, 2023). "We also knocked down ZEB1 in other breast cancer cell lines, including BCX-011CL and SUM159, and confirmed that ZEB1 deficiency increased TROP2 levels in the cells." (PMID 37567892, 2023). "One study reported suppression of POLQ expression by binding the transcription factor zinc finger E-box binding homeobox 1 (ZEB1) to the POLQ promoter in breast cancer cells." (PMID 36835031, 2023). "The M13HS tumor hybrids, which were derived from spontaneous fusion events between the M13SV1-EGFP-Neo breast epithelial cells and HS578T-Hyg breast cancer cells, express ZEB1 and exhibit prospective cancer stem cell properties." (PMID 38139138, 2023). "ZEB1 induces resistance to epirubicin in breast cancer, oxaliplatin in esophageal cancer, docetaxel in prostate cancer, and gemcitabine in pancreatic cancer." (PMID 37370762, 2023). "In literature, the function of several ZEB1‐circRNAs, including hsa_circ_0000228, has been described in several types of cancer, such as cervical cancer, breast cancer and hepatocellular carcinoma." (PMID 37408496, 2023). "We have demonstrated in a previous study that the M13HS-2 and -8 tumor hybrids co-expressed SNAIL and ZEB1, while parental human M13SV1-EGFP-Neo breast epithelial cells were only positive for SNAIL and human HS578T-Hyg breast cancer cells only expressed ZEB1." (PMID 38139138, 2023). "AXL also induces the upregulation of ZEB1 (zinc finger E-box binding homeobox 1) transcription and mediates the drug resistance of breast cancer to doxorubicin through the same pathway." (PMID 37328828, 2023). "Previous research has discovered that ZEB1 promotes breast cancer cell proliferation by down-regulating p21 and up-regulating CDK2 and CDK4 through the cell cycle." (PMID 37978168, 2023). "To further characterize stemness of these breast cancer cells, we induced the expression of Zeb1 by doxycycline in these two populations of cells (low and high mCherry)." (PMID 37372954, 2023). "In contrast, in our MCF-7-based breast cancer cell model, the ectopic expression of Zeb1 confers a partially mesenchymal phenotype." (PMID 37372954, 2023). "LncRNA MIR497HG is regulated by various factors in breast cancer, in which ZEB1 and ERα play important roles." (PMID 37901333, 2023). "Since EMT was reported to be associated with cancer stem cell features and Zeb1 was implicated in this process, we decided to investigate the protein composition of Zeb1 interactome in breast cancer stem cells." (PMID 37372954, 2023). "Significantly lower miRNA-34a-5p and miRNA-200c-3p expression levels were observed in the HS578T-Hyg breast cancer cells, M13HS-2 and -8 tumor hybrids and their ZEB1-KO variants, in comparison to the M13SV1-EGFP-Neo breast epithelial cells." (PMID 38139138, 2023). "miR‐205 was found to be lower in radioresistant breast cancer, while upregulation of miR‐205 targeted ZEB1 and Ubc13 to improve radiosensitivity in preclinical models of breast cancer." (PMID 37206240, 2023).
breast carcinoma (continued). "In contrast, the scratch/ wound was significantly faster closed by the HS578T-Hyg ZEB1-KO cells than by the HS578T-Hyg wildtype breast cancer cells." (PMID 38139138, 2023). "The expression of PAX5 was significantly down-regulated in breast cancer tissues, while the expression levels of DNMT1 and ZEB1 were both up-regulated in breast cancer tissues, compared with normal tissues." (PMID 37403081, 2023). "Taken together, PAX5-miR-142-DNMT1/ZEB1 formed a feedback loop in regulation of breast cancer progression." (PMID 37403081, 2023). "Zinc finger E-box binding homeobox 1 (Zeb1), a transcription factor, has been demonstrated to reprogramme TAMs to become immunosuppressive M2-like TAMs in human breast cancer samples." (PMID 37491279, 2023). "Consistent with this, MDM2 overexpression has been found to enhance the expression of EMT markers, such as ZEB1, via the B‐Raf signaling pathway in glioma, lung cancer, and breast cancer cells." (PMID 37138218, 2023). "In summary, we demonstrate the existence of PAX5-miR-142-5p/3p-DNMT1/ZEB1 feedback loop in regulation of breast cancer." (PMID 37403081, 2023). "In conclusion, YTHDF2 and FTO increase the stability and expression of ZEB1 mRNA, leading to drug resistance and high aggressiveness of breast cancer cells." (PMID 38031146, 2023). "The migratory activity of the HS578T-Hyg ZEB1-KO cells was rather slightly decreased as compared to the HS578T-Hyg breast cancer cells (HS578T-Hyg: 230 ± 12 cells vs. HS578T-Hyg ZEB1-KO: 158 ± 7 cells)." (PMID 38139138, 2023). "For example, to drive hybrid E/M tumors to a fully mesenchymal phenotype in breast carcinoma cells requires ZEB1 expression." (PMID 37370762, 2023). "We previously revealed an unusual role of ZEB1 in the S100A8/A9-mediated metastasis in breast cancer cells that expressed ZEB1 at a significant level and showed that the ZEB1 was activated on the MCAM-downstream pathway upon S100A8/A9 binding." (PMID 36910659, 2023). "In summary, we exhibited a feedback regulation loop formed by PAX5, miR-142, and DNMT1/ZEB1, which play crucial roles in breast cancer development." (PMID 37403081, 2023). "For example, SNAIL triggers metastasis in breast cancer, whereas ZEB1 favors metastasis in pancreatic cancer." (PMID 36936987, 2023). "When these MSCs were co-cultured with a breast cancer cell model, there was a coincident reduction in EMT-associated genes (e.g., ZEB1/2, TWIST1, SNAIL, FOXC2, N-Cadherin)." (PMID 36940196, 2023). "ER-positive breast cancers show higher expressions of miR-200 family members despite the fact that their negative regulator ZEB1 is a transcriptional target of ER." (PMID 37504297, 2023). "Recently, epithelial–mesenchymal transition transcriptional factors (SNAIL, SLUG, and ZEB1) induce primary cilia formation in mammary tumor-initiating cells of claudin-low breast cancers." (PMID 37006607, 2023). "Metastatic breast cancer cells with lower ZEB1 expression levels develop an epithelial phenotype and lose the mesenchymal/motile phenotype." (PMID 35454770, 2022). "In another study, FOXA2 has been reported to inhibit mesenchymal transition in breast cancer through E-cadherin and ZEB-1 regulation." (PMID 36289750, 2022). "Previous studies have demonstrated that ELK3 regulates breast cancer metastasis through Zeb-1, MT1-MMP, and GATA3 gene-mediated signaling pathways." (PMID 35409069, 2022). "ZEB1 physically interacts with ATM in SUM159-P2 human breast cancer cells, such that ATM depletion significantly downregulates ZEB1 and checkpoint kinase 1 (CHK1) protein levels." (PMID 35454770, 2022). "The expression of ZEB1 is reportedly regulated by Ets1 in breast cancer cells and positively correlated with the mesenchymal phenotypes in breast cancer and OSCC cells." (PMID 35451213, 2022).